LRP1 (LDL receptor related protein 1)
Diseases named in the same sentence as LRP1 in open-access papers (continued):
Sharing a sentence is not in itself a finding about the gene and the disease.
tumor (continued). "Stress fibers, membrane protrusions and projections of fast-invading tumor cells also appeared to be highly regulated by the LRP-1-mediated regulation of ERK/JNK activation." (PMID 20644732, 2010). "Considering its well-known function in the control of matrix proteolysis, LRP-1 was initially proposed as a novel tumor suppressor." (PMID 20644732, 2010). "Surface modifications using sugars (e.g., galactose, mannose), peptides (e.g., angiopep-2), or molecules that recognize receptors overexpressed on tumor cells (e.g., LRP1, TfR) enable them to specifically target glioma cells, microglia, or tumor-associated macrophages (TAMs)." (PMID 40574001, 2025). "Even if a drug successfully penetrates the BBB, tumor cells may develop resistance through multiple mechanisms, such as P-gp and LRP-1-mediated drug efflux." (PMID 40006075, 2025). "Similarly, we found that LRP1 protein levels in HCC tissues were significantly lower than those in normal liver tissues in the Clinical Proteomic Tumor Analysis Consortium (CPTAC) dataset." (PMID 39405202, 2024). "Additionally, our study unveiled correlations between LRP1 expression and tumour purity across different cancer types, indicating its potential involvement in tumour–stromal interactions and progression." (PMID 39063239, 2024). "The distinct functional roles of LRP1 in OC may arise from inherent tumour heterogeneity or the limited single-cell data available for analysis." (PMID 39063239, 2024). "Conversely, the increased tumorigenic capacity in subcutaneous xenografts with LRP1 knockdown was substantially reversed by lentivirus‐mediated overexpression of the LRP1 β∆‐chain, leading to a decrease in the tumor growth rate and tumor weight to a level comparable to that in the control group." (PMID 39405202, 2024). "Lrp1 may be related to tumor growth and metastasis, particularly by modulating three extracellular tumor environments." (PMID 39702344, 2024). "Second, pJNK and MMP2 can also promote tumor invasion and migration in other malignancies, and it may thus be necessary to search for LRP1–SNRNP25-specific downstream signaling molecules." (PMID 38678020, 2024). "LRP1 interacts with a myriad of ligands and co-receptors, mediating crosstalk between cancer cells and their surrounding stroma, thus impacting pathways critical for tumour growth and dissemination." (PMID 39063239, 2024). "Our KEGG and GSEA analyses revealed that in OC, elevated LRP1 expression is primarily associated with actin filament-based processes, amyloid beta clearance, aorta development, coagulation, and epithelial–mesenchymal transition, suggesting a pivotal role for LRP1 in tumour progression." (PMID 39063239, 2024). "By drawing parallels with known molecular mechanisms, such as in phagocytosis between macrophages and tumor cells, we might be able to map out a new LRP1 mechanism to reveal its function(s) in T cells." (PMID 37020553, 2023). "The integrated cohort confirmed our findings, suggesting that LRP1 expression level can contribute to the diversity of the tumor microenvironment by influencing multiple pathways related to the tumor microenvironment and creating an environment conducive to tumor progression." (PMID 37153545, 2023). "By the crucial relationship of LRP1 expression with the infiltration of macrophages and CAFs abundance, our manuscript indicated that LRP1 was an immune suppressive factor in the tumor microenvironment of BLCA, further influencing patients’ responsiveness to ICBs therapy." (PMID 37153545, 2023). "However, it has been shown that in gliomas midkine (MDK) can bind to LRP1 on tumor-infiltrating CD8+ T cells leading to increased CCL4 expression on T cells." (PMID 37020553, 2023).
tumor (continued). "In addition, the binding of PAI-1 and LRP1 can stimulate vitronectin expression in tumor cells, which further regulates cell motility." (PMID 36605486, 2023). "With tumor progression, LRP1 deficient DCs failed to present tumor antigens to T cells to stimulate anti-cancer immune response." (PMID 37020553, 2023). "In addition,the binding of lactoferrin to LRP-1 expressed on tumor cells alsodramatically increased the cellular uptake of this nanomedicine." (PMID 37901179, 2023). "Five potential tumor neoantigens (LRP1, TCF12, DERL3, WIPI2, and TSHZ3) were identified in GBM by selecting genes both with abnormal alternative splicing (upregulated) and gene frameshift mutations, in which LRP1 was significantly associated with APCs." (PMID 37978542, 2023). "Hence, LRP-1 is crucial for the tumor cells' survival and aggressive biological behavior which is maintain through the regulation of high intracellular cholesterol import." (PMID 36267880, 2022). "However, the addition of both Gefitinib and mAb1G6-D7 showed additive effect on inhibition of the tumour cell migration, similar to the LRP-1 downregulated cells." (PMID 35835845, 2022). "In addition to the tumor cell, LRP-1 positivity was also noted in the proliferating endothelial cell." (PMID 36267880, 2022). "Moreover, specific genetic deletion of the receptor for PRSS2, LRP1, in myeloid cells recapitulates the tumor-inhibitory effects of silencing PRSS2." (PMID 36575174, 2022). "Considering the predominant immunopositivity of LRP-1 in the tumor tissue only and its high expression in GBM cases, it may be an essential adjunct in routine diagnosis, especially in small biopsies." (PMID 36267880, 2022). "The gene cluster (LRP1, ACVR2A, and SETBP1) could be a good biomarker of these patients with a family risk, which was characterized by right-sidedness, high tumor mutational burden, and high microsatellite instability." (PMID 35814400, 2022). "Certain CD31-stained shLRP-1 tumor sections exhibited large structures resembling hemorrhagic lakes rather than vessels, but anastomoses were also observed, highlighting a marked vascular anarchy when LRP-1 is repressed in MDA-MB-231." (PMID 34680548, 2021). "LRP‐1 (TβR‐V) acts as a tumor suppressor for epithelial cells." (PMID 34485840, 2021). "Notably, the expression levels of both MAOB and LRP1 were downregulated in tumor samples compared with normal samples in the TCGA and GEO databases, but the expression of FASN was upregulated." (PMID 34819038, 2021). "As a mecanosensor of the tumor microenvironment, LRP-1 temporal expression during tumorigenesis could modulate the sensitivity of cells in response to stresses such as hypoxia." (PMID 34680548, 2021). "To explore how LRP-1 influences tumor progression and angiogenesis, we investigated whether a LRP-1-silenced MDA-MB-231 secretome could modulate the angiogenic potential of endothelial cells (ECs)." (PMID 34680548, 2021). "As with uPAR, LRP1 mitigates prosurvival signals in tumor cells." (PMID 33669052, 2021). "uPA and tPA receptors, such as uPAR, LRP1, integrins, and annexin II (AnxII), modulate intracellular signaling pathways, just like NF-κB, establishing a premetastatic niche, which is an environment prepared for tumor cell colonization in distant organ sites." (PMID 33669052, 2021). "LRP1 is ubiquitously expressed by multiple cells, including VSMCs, macrophages, hepatocytes, epithelial cells, retinal Müller glial cells, neurons, astrocytes, fibroblasts, adipocytes, tumor cells, endothelial cells, neutrophils and T cells." (PMID 34124208, 2021). "Here, we showed that LRP-1 plays a more decisive role, not only by contributing to cell survival and proliferation; it modulates (directly or indirectly) the angiogenic balance through its pivotal roles within the tumor microenvironment." (PMID 34680548, 2021).
tumor (continued). "The endocytosis of multiple extracellular ligands of LRP1, including apolipoprotein E (ApoE)- and lipoprotein lipase-enriched lipoproteins, thrombospondin, and plasminogen activators, is important in vascular biology and tumor progression." (PMID 34124208, 2021). "Its specific binding to LRP1 stimulates tumor development and metastatic lung colonization." (PMID 32850302, 2020). "Moreover, multiplex immunohistochemistry staining of the HCC tissue microarray showed positive associations between the expression levels of BAP31, SERPINE2, its downstream gene LRP1, and a tumor proliferation marker, Ki-67." (PMID 33363167, 2020). "Finally, we identified a new molecular way that controls the cell-surface expression of DDR1 and suggested an additional role of LRP-1 as a key sensor of the tumor microenvironment." (PMID 32582700, 2020). "Additionally, LRP1 has been shown to be upregulated in various cancers and promotes cancer cell invasion, migration and tumor progression through the activation of focal adhesion kinase (FAK), Akt and Erk1/2 pathways." (PMID 32244557, 2020). "LRP1 can exert a dramatic control of tumor cell plasticity and migratory capacities." (PMID 32850302, 2020). "Cell surface receptors known to be bound with ex-HSP90 are (i) CD91/LRP1/A2MR expressed on tumor cells, immune cells, and EVs, (ii) toll-like receptors (TLRs), (iii) scavenger receptor expressed by endothelial cells-1 (SREC-1), and (iv) CD94/KLRD1 expressed on killer cells." (PMID 31533245, 2019). "By eliciting control over MMP extracellular levels, Lrp1 additionally modifies cell adhesion and migration capabilities that are crucial not only for processes like wound healing and angiogenesis but also for tumor growth." (PMID 30931303, 2019). "Therefore, LRP1 influence on tumor cell migration and invasion likely depends on the tumor cell type and the specific extracellular proteins involved in these processes." (PMID 29507659, 2018). "Low LRP1 IHC score in tumor cells (score ≤ 4) was predictor of poor OS (p = 0.003)." (PMID 29507659, 2018). "Indeed, stage IV patients with low LRP1 IHC score in tumor cells had shorter OS, even when treated with bevacizumab." (PMID 29507659, 2018). "This reduced expression of LRP1 by miR-205 led to decreased tumor cell migration." (PMID 29507659, 2018). "Numerous studies have suggested a role for LRP1 in regulation of tumor growth and progression." (PMID 29507659, 2018). "Albeit speculative at present, we propose that the molecular mechanism linking PDGF, Lrp1, and RANKL, all of which have been independently implicated in various tumors, may help to also understand the ways of reducing tumor-associated osteolysis." (PMID 29507818, 2018). "A2M* is a ligand of LRP1, which has been shown to regulate cytoskeleton organization, interaction with the extracellular matrix and affects migration and invasion of various non-tumour and tumour cells." (PMID 29281661, 2017). "Regarding the heterogeneous results of ratio smLRP1/LRP1, different stage and origin of the tumours might contribute to varying results." (PMID 28662213, 2017). "LRP1 is also critically involved in many processes that drive tumorigenesis and tumor progression." (PMID 29146996, 2017). "The fact that RAP is mainly present in the cytosolic compartment and only few molecules appear associated to LRP1 at the outer cell surface, it is reasonable to assume that A2M* plays a dominant role in regulation of CD44 expression in tumour cells compared to RAP." (PMID 29281661, 2017). "LRP1 is critically involved in tumor cell invasion and tumor progression." (PMID 29138479, 2017). "The inhibition of LRP1 expression in invasive tumor areas is an important finding." (PMID 29146996, 2017). "Therefore, the function of LRP1 in cell migration and invasion likely depends on the tumor cell type and the specific extracellular proteins involved in these processes." (PMID 29138479, 2017).
tumor (continued). "Although long debated, it is now well established that LRP-1 may control critical events influencing tumor cell attachment, spreading, migration and invasion." (PMID 29108253, 2017). "Taken together, our results are in favor of a role of CXCR3 and LRP1 in tumor cell invasion and infiltration, where LRP1 is downregulated at the invasive areas to allow accumulation of CXCR3 at the cell membrane leading to a sustained CXCR3 activation and increased tumor cell invasion." (PMID 29146996, 2017). "Thus, low expression of LRP1 on the cell surface couples to increased expression and bioactivity of uPA and promotes tumor cell invasion." (PMID 26738504, 2016). "However, some investigations suggest that low expression of LRP1 can also promote tumor cell progression." (PMID 26738504, 2016). "In addition, LRP1 has dual effects on tumor cell invasion and migration, reinforcing that the tumor cell-specific activity of LRP1 must be studied in the future." (PMID 26738504, 2016). "The ability of LRP1 to promote endocytosis and deliver cell signaling suggests that LRP1 may play multiple roles in tumorigenesis and tumor progression." (PMID 26738504, 2016). "Consequently, these results highlight a potential tumor suppressive function of miR-205 via regulating the expression of LRP1." (PMID 26738504, 2016). "In the breast tumor microenvironment, it was reported that the pro-cath-D protease, highly secreted by tumor cells, may trigger mammary fibroblast outgrowth in a paracrine LRP1-dependent manner." (PMID 26617523, 2015). "Some studies indicated that LRP-1 facilitates tumor progression, while others showed that LRP-1 may have opposite effects." (PMID 25514242, 2014). "LRP1 offered a possible strategy for tumor molecular therapy." (PMID 22427881, 2012). "Therefore, the LRP1 function in tumor cell migration and invasion likely depends on the tumor cell type and the specific extracellular proteins involved in these processes." (PMID 22427881, 2012). "Because of the importance of extracellular proteases in tumour progression and metastasis, this activity may account for the critical role of LRP1 in aggressive tumours." (PMID 22027709, 2011). "Importantly, the homogeneous distribution of ANG1005 throughout the tumour mass also argues that an active transport process, such as one mediated by LRP1, participates in the transport under the unique conditions present in this aggressive tumour type." (PMID 22027709, 2011). "Finally, changes in microenvironmental conditions near tumour cells that increased LRP1 expression simultaneously increased uptake of Angiopep-2 and ANG1005." (PMID 22027709, 2011). "Previously reported mechanisms of action for LRP1b, including the regulation of the urokinase (uPAR) and platelet-derived growth factor (PDGF) receptor trafficking at the membrane level, overlap with the functions of expressed and unmutated LRP1 in tumor tissues." (PMID 20383322, 2010). "We recently described a key role for LRP-1 in tumor progression." (PMID 20644732, 2010). "The presence of LRP-1 at the leading edge could therefore orchestrate polarization and support directional migration of tumor cells." (PMID 20644732, 2010). "Moreover, we uncover a novel regulatory role of LRP1, especially its β‐chain, in modulating the association between UFL1 and OGA to maintain OGA stability and exert tumor‐suppressing activity by abating NF‐κB O‐GlcNAcylation and inhibiting its downstream signaling pathway." (PMID 39405202, 2024). "A previous study showed that liposomal therapy targeting macrophage LRP1 effectively suppresses the crosstalk between tumor metabolism and immune evasion via glycolysis inhibition and immune normalization, resulting in reduced lactic acid production and switching TAMs to an anti-tumor phenotype." (PMID 37153545, 2023).
tumor (continued). "This is because the inhibition of LRP1 receptor–CXCR3-A binding leads to reduced CXCR3-A internalization, which supports our hypothesis that upregulation of LRP1 in the tumor may have the opposite effect, promoting CXCR3-A endocytosis and reducing GBM invasion." (PMID 38104126, 2023). "Our results reveal that endocytosis plays an unexpected role in gefitinib action and that expression level of endocytosis proteins such as DNM2, LRP-1 or Rab5 could be relevant biomarkers to predict TKI efficiency in limiting dissemination of GBM cells from tumour spheroids." (PMID 34831480, 2021). "However, other studies support a more complex view of LRP1 functions in tumor cells." (PMID 32850302, 2020). "However, the role of LRP1 varies from one tumor type to another." (PMID 29507659, 2018). "Thus, the differential expression of LRP1 between tumor and stromal cells might confer survival and spreading benefits for tumor cell in some tumor types including CRC." (PMID 29507659, 2018). "Interestingly, the reduction of YAP-induced inhibition of tumor growth could be gradually rescued by overexpression of the LRP1 plasmid, demonstrating that LRP1 is an important downstream effector of YAP in vivo." (PMID 29138479, 2017). "However, LRP1 is a controversial protein in the pathogenesis of tumor development." (PMID 29138479, 2017). "In addition, positive feedback signaling from eHsp90 further activates AKT and promotes recruitment of LRP1 to EphA2, thereby strengthening this signaling pathway and highlighting a novel mechanism of LRP1-mediated regulation of tumor cell migration and invasion." (PMID 26738504, 2016). "Therefore, we consider that the LRP1 function in tumor cell migration and invasion may depend on the tumor cell type and the specific extracellular proteins involved in these processes." (PMID 22427881, 2012). "Thus, we propose that LRP1 might regulate tumor migration and invasion by altering the level of MMP9." (PMID 22427881, 2012). "LRP1 may offer a possible strategy for tumor molecular therapy." (PMID 22427881, 2012). "We demonstrated, for the first time, that DS markedly inhibits tumor growth and sensitizes tumors to PD-1 blockade by activating TBK1-dependent IFN-I signaling through targeting LRP1." (PMID 40625660, 2025). "Leveraging LRP1-mediated transcytosis, ANG1005 achieves active BBB traversal and precisely delivers paclitaxel to intracranial tumor microenvironments, enabling localized drug accumulation." (PMID 41219968, 2025). "The low-density lipoprotein receptor-related protein 1 (LRP1, CD91) is the ligand for CRT and is expressed on the surface of phagocytes to promote phagocytosis of tumor cells." (PMID 40835598, 2025). "DS specifically binds to LRP1, disrupts lysosomal function, and activates TBK1-dependent IFN-I signaling, thereby reprogramming the TME and enhancing the tumor’s response to anti-PD-1 or STING agonist treatment." (PMID 40625660, 2025). "Further multivariate analysis unveiled significant insights: LRP1, PAEP, PI3, OBP2A, and IL27RA genes exhibited higher levels in the tumour group, whereas FOS, PDGFRA, and FGF7 showed higher expression in normal ovarian tissue (all p < 0.001)." (PMID 39063239, 2024). "Our stromal score analysis showed a favourable link between the expressions of genes such as LRP1, FGF7, FOS, PI3, PAEP, and PDGFRA and tumour purity in our investigation of the effect of IRGs on OC’s TME." (PMID 39063239, 2024). "LRP1, AKT2, PI3, IL27RA, OBP2A, and PAEP were found to be more expressed in OC tumour samples than in normal tissues." (PMID 39063239, 2024). "In nude mice injected with cells overexpressing LRP1–SNRNP25, the tumor volume and weight were significantly decreased after SP600125 treatment compared with DMSO treatment (P < 0.05)." (PMID 38678020, 2024).